TTYH1 (tweety family member 1)
Description:
Calcium-independent, swelling-dependent volume-regulated anion channel (VRAC-swell) which plays a pivotal role in the process of regulatory volume decrease (RVD) in the brain through the efflux of anions like chloride and organic osmolytes like glutamate. [Isoform 3]: Ca(2+)-independent, swelling-activated chloride channel, possibly involved in regulation of cell volume.
Tractability: Antibody: UniProt places it where antibodies can reach, with high confidence; its Gene Ontology location is reachable by antibodies, with high confidence; UniProt predicts a signal peptide or a membrane-spanning region; the Human Protein Atlas places it where antibodies can reach. PROTAC: its protein half-life has been measured.
Gene: Protein-coding gene on chromosome 19 (54,415,219 to 54,436,904, forward strand). Ensembl gene ENSG00000167614.
Subcellular location: Cell membrane
Subcellular location (Human Protein Atlas): Nucleoplasm; Plasma membrane
Pathways (Reactome):
Transport of small molecules: Stimuli-sensing channels
Gene Ontology:
Molecular function: chloride channel activity; protein binding; volume-sensitive anion channel activity; volume-sensitive chloride channel activity; intracellularly calcium-gated chloride channel activity; iron ion transmembrane transporter activity; calcium ion binding
Biological process: chloride transport; iron ion transport; L-glutamate transmembrane transport; monoatomic ion transmembrane transport; chloride transmembrane transport; iron ion transmembrane transport
Cellular component: plasma membrane; membrane; smooth endoplasmic reticulum membrane; filopodium membrane; filopodium tip; synapse
Genetic constraint (gnomAD): Loss-of-function variants: 33 observed, 51.66 expected, observed/expected ratio (o/e) 0.64, 90% interval 0.48 to 0.85. The synonymous counts are far from expectation, so gnomAD's model fits this gene poorly and the ratio says little. Missense variants: 538 observed, 535.25 expected, observed/expected ratio (o/e) 1.01, 90% interval 0.94 to 1.08. Synonymous variants: 308 observed, 251.26 expected, observed/expected ratio (o/e) 1.23, 90% interval 1.12 to 1.35.
Homologues: Orthologues: chimpanzee TTYH1 (94% identical), pig TTYH1 (90% identical), rat Ttyh1 (89% identical), mouse Ttyh1 (89% identical), dog TTYH1 (81% identical), macaque TTYH1 (77% identical), guinea pig TTYH1 (72% identical), tropical clawed frog ttyh1 (61% identical), zebrafish ttyh1 (49% identical), Drosophila melanogaster tty (25% identical), Drosophila melanogaster CG3638 (24% identical), Caenorhabditis elegans ttyh-1 (23% identical). Paralogues in human: TTYH2 (42% identical), TTYH3 (38% identical).
Diseases named in the same sentence as TTYH1 in open-access papers:
TTYH1 is named in the same sentence as 29 diseases in open-access papers, as found by Europe PMC text mining. Sharing a sentence is not in itself a finding about the gene and the disease. The quoted sentences say what the papers report.
glioma (10 papers, 2020 to 2025). A benign or malignant brain and spinal cord tumor that arises from glial cells (astrocytes, oligodendrocytes, ependymal cells). "Previous studies implicated Ttyh1 in pathological conditions, such as epilepsy and glial tumor progression." (PMID 34173119, 2021). "Cells with one to two tumor microtubes were more motile than those with more than four, suggesting TTYH1’s role in facilitating glioma propagation, potentially through tumor microtube-associated mechanisms." (PMID 34262434, 2021). "Additional evidence for the role of tweety genes in gliomas comes from the association between TTYH1 and tumor microtube formation in glioblastoma cells." (PMID 34262434, 2021). "Consequentially, Ttyh1 downregulation in glioma cells caused reduced tumor progression and prolonged survival of mice." (PMID 32244839, 2020). "An increase in Ttyh1 expression has been implicated in glial tumors and epilepsy." (PMID 34173119, 2021). "Notably, TTYH1 shRNA knockdowns in glioblastoma cell lines caused reduced glioma invasiveness, abnormal neurite membrane protrusion morphology, decreased tumor size, and increased survival in mice." (PMID 34262434, 2021). "In particular, TTYH1 knockdown reduced invasiveness of glioma and decreased tumor size, and increased survival in mice." (PMID 35455021, 2022). "Among the TTYH family, TTYH1 is highly expressed in several cancer cells, such as glioma, breast, and gastric cancer cells." (PMID 35455021, 2022). "Ttyh1 expression is induced under pathological conditions, such as epilepsy, triple-negative breast cancer, glial tumors, and in activated astrocytes in the epileptic brain." (PMID 34173119, 2021). "Upregulation of TTYH1 has been validated in various cancers, including glioma, astrocytoma, and other cancers." (PMID 34729116, 2021). "In cancer cells of glial origin, TTYH1 localized to tips of tumor microtubes, neurite-like long membranous extensions involved in proliferation, invasion, and network formation among glioma cells." (PMID 34824283, 2021). "Interestingly, TTYH1 drives tumor microtubule-mediated colonization of glioma cells and serves as volume-regulated anion channels (VRACs) in several cancer cells such as SNU-601 gastric cancer cells and HepG2 liver cancer cells." (PMID 35455021, 2022). "Finally, knockdown of TTYH1 within the tumor cells resulted in altered morphology of cellular protrusions, resulting in “beading” of neurites and glioma tumor microtubes, and reduction of tumor growth and improved survival in vivo." (PMID 34824283, 2021). "The Ttyh1 transcript, a biomarker of the recently identified the Ttyh1-dependent subset of the tunneling microtubes with widths up to 2.5 μm, exhibited significant overexpression in gliomas compared to normal brain." (PMID 33096700, 2020). "However, it was reported that Ttyh1 is downregulated in 1p/19q-co-deleted versus 1p/19q intact human gliomas by utilizing RNA-Seq gene-expression analysis." (PMID 33096700, 2020). "Additionally, in vivo two-photon microscopy in mice implanted with human glioma cells showed that TTYH1-positivity was tumor microtube count-dependent as higher TTYH1-positivity was found in glioma cells with one to two tumor microtubes compared to those with more than four." (PMID 34262434, 2021). "According to the recent research in mouse models, Ttyh1 also plays a key role in the growth of invasive non-connecting TMs, while the knockdown of Ttyh1 contributed to a dramatically declined proportion of invasive TM-non-connected glioma cells." (PMID 35847909, 2022). "Furthermore, glioblastomas with 1p/19q chromosome arms codeletions (associated with diminished glioma propagation and impaired tumor microtube formation and function) show TTYH1 and TTYH2 downregulation and TTYH3 upregulation compared to 1p/19q non-codeleted gliomas." (PMID 34262434, 2021).
gastric cancer (4 papers, 2021 to 2024). A primary or metastatic malignant neoplasm involving the stomach. "First, ICl,swell was not affected by shRNA-mediated knockdown of LRRC8A but, in contrast, was largely abolished by double knockout of TTYH1 and TTYH2 in gastric cancer SNU-601 cells." (PMID 38238667, 2024).
glioblastoma (4 papers, 2019 to 2024). The most malignant astrocytic tumor (WHO grade IV). "A strong association exists between TTYH1 and brain cancers, particularly glioblastoma." (PMID 34262434, 2021). "In studies involving knockdown of Ttyh1, a substantial reduction in the number of microinvasive glioblastoma cells was observed, underscoring the importance of Ttyh1 in promoting invasive behaviour." (PMID 38567664, 2024). "Immunocytochemistry showed human glioblastoma stem cells in vitro having punctate TTYH1 localization concentrated at the membrane and growth cone-like tips of tumor microtubes, suggesting TTYH1’s possible involvement in tumor microtube growth." (PMID 34262434, 2021). "Additionally, linear regression revealed that Ttyh1 levels quantified and analyzed using western blot positively correlated with glioblastoma invasiveness in vivo." (PMID 34262434, 2021). "For example, TTYH1 and TTYH2 were upregulated in infiltrating compared to core neoplastic cells in glioblastoma patients." (PMID 34262434, 2021). "In addition, TTYH1 and TTYH2 are upregulated in glioblastoma cells and colon cancer cells, respectively." (PMID 31181821, 2019).
brain tumors (3 papers, 2017 to 2025). "C19MC overexpression has been reported in embryonal pediatric brain tumors caused by fusion with TTYH1 or focal genomic amplification." (PMID 27844328, 2017). "In particular, elucidation of the VRAC functions of TTYH1 as a VRAC could lead to improved treatment of brain tumors, which are currently associated with high mortality rates and limited therapeutic options." (PMID 31181821, 2019).
breast carcinoma (3 papers, 2015 to 2023). "At the same time, higher expression of 4 important genes (NMU, COL2A1, PRAME, and TTYH1) that contribute to higher breast cancer lung metastasis was observed in the tumors from Black women compared to the tumors from white women with an adjusted p-value of 0.000664734 (one-way ANOVA)." (PMID 36702853, 2023). "A Kaplan-Meier analysis also demonstrated a positive correlation between TTYH1 expression and life expectancy in triple-negative breast cancer patients, conferring TTYH1 as a potential disease biomarker and suggesting that TTYH1 may hinder breast cancer progression." (PMID 34262434, 2021). "In contrast with TTYH1, TTYH2 and TTYH3 have only been studied in breast cancer through RNA-Seq and microarray analyses with TTYH2 showing downregulation and TTYH3 showing upregulation in breast cancer-associated cells and tissues." (PMID 34262434, 2021). "These genes (COL9A1, ITGB8, ITGB6, TTYH1, RET, etc.)enriched in the cell adhesion may serve as important indicators of different types of breast cancer." (PMID 26273658, 2015).
colon cancer (3 papers, 2019 to 2022). "In contrast with the functional studies conducted on TTYH2 in colon cancer, TTYH1 and TTYH3 have only been studied in colon cancer through gene expression assays." (PMID 34262434, 2021).
embryonal tumor (3 papers, 2015 to 2025). "The presence of C19MC amplification has been also highlighted for embryonal tumors as it has been shown that embryonal tumor oncogenesis is driven genetically by the fusion of TTYH1 to C19MC involved in fetal neural development." (PMID 25652781, 2015). "SE-miR-512–1 can be governed by TTYH1 and activates the miR-512–1-LIN28A-MYCN circuit to control the development of embryonal tumors with multilayered rosettes." (PMID 37501079, 2023).
osteosarcoma (3 papers, 2021 to 2022). A usually aggressive malignant bone-forming mesenchymal neoplasm, predominantly affecting adolescents and young adults. "Therefore, the potential role of TTYH1 in the clinical evidence associated with the progression of osteosarcoma should be examined in future studies." (PMID 35455021, 2022). "Overall, these data suggested that TTYH1 can play an important role in the cell migration and invasion of osteosarcoma cells." (PMID 35455021, 2022). "To study the effects of TTYH1 overexpression in osteosarcoma cell lines, we transfected TTYH1-GFP into SaOS2 cells and confirmed TTYH1 expression using RT-PCR analysis." (PMID 35455021, 2022). "Functional roles of TTYH1 with binding proteins in osteosarcoma should be further studied in future studies." (PMID 35455021, 2022). "Further studies will be required to examine how TTYH1 silencing is involved in the reduction of EMT phenotype in osteosarcoma cells." (PMID 35455021, 2022). "Here, we report that deficient TTYH1 expression results in the inhibition of the migration and invasion of U2OS human osteosarcoma cells." (PMID 35455021, 2022). "First, the results of RT-PCR showed that mRNA expression of TTYH1 was the highest in U2OS cells among three different osteosarcoma cell lines and control Fob1.19 osteoblast cells." (PMID 35455021, 2022). "Here, we found that TTYH1 is highly expressed in human osteosarcoma U2OS cells and that the knockdown of TTYH1 did not affect the proliferation of U2OS cells but significantly suppressed the migration and invasion of U2OS cells." (PMID 35455021, 2022). "In contrast with TTYH2, TTYH1 and TTYH3 have only been studied in osteosarcoma through microarray and RNA-Seq experiments showing TTYH1 downregulation and TTYH3 upregulation." (PMID 34262434, 2021). "Our findings suggest that TTYH1 could be used as a potential target for the treatment of osteosarcoma." (PMID 35455021, 2022). "Taken together, our findings suggest that silencing of TTYH1 expression reduces migration and invasion of U2OS cells and that TTYH1 may act as a potential molecular target for osteosarcoma treatment." (PMID 35455021, 2022). "Thus, our data indicated that TTYH1 was endogenously expressed and that knockdown of TTYH1 significantly reduced the migration and invasion of human osteosarcoma U2OS cells." (PMID 35455021, 2022). "In particular, the elucidation of the functions of TTYH1 in U2OS cells could lead to the development of improved treatment strategies for osteosarcoma, presenting with high metastasis rates and limited therapeutic options." (PMID 35455021, 2022). "In addition, the clinical significance of TTYH1 in osteosarcoma is still unclear, although our data showed involvement of TTYH1 in the migration and invasion of osteosarcoma cell lines." (PMID 35455021, 2022). "Next, to determine whether TTYH1 expression levels also correlate with the cancerous properties of osteosarcoma cells, we used two different siRNAs constructs against TTYH1 (siTTYH1) and examined the gene silencing efficiency of these siRNAs in osteosarcoma cells." (PMID 35455021, 2022). "To explore whether TTYH1 expression is involved in the progression of osteosarcoma, we investigated the endogenous expression of TTYH1 at mRNA and protein levels using RT-PCR and Western blotting, respectively, in three different human osteosarcoma cell lines (U2OS, SaSO2, and MG-63)." (PMID 35455021, 2022). "Deficiency of TTYH1 results in downregulation of EMT-related pathways and expression of transcription factors, implying that TTYH1 could be a potential target for the treatment of osteosarcoma." (PMID 35455021, 2022). "However, the role of TTYH1 in the progression of osteosarcoma remains unknown." (PMID 35455021, 2022). "Taken together, these results revealed that silencing of TTYH1 regulates the migration and invasion of U2OS osteosarcoma cells and reduces the expression of MMP2/9, N-cadherin, ZEB, and SNAIL." (PMID 35455021, 2022).
osteosarcoma (continued). "In this study, we investigated the correlation between TTYH1 expression and cancer progression of U2OS human osteosarcoma cells." (PMID 35455021, 2022). "On the basis of our previous and current studies, we believe that TTYH1 and TTYH2 can serve as potential therapeutic targets in osteosarcoma." (PMID 35455021, 2022). "Silencing of TTYH1 inhibited the migration and invasion of the U2OS osteosarcoma cells and reduced the expression of epithelial-mesenchymal transition (EMT)-related factors such as SNAIL, Zinc E-Box Binding Homeobox 1 (ZEB1), matrix metalloproteinase 2 (MMP2), MMP9, and N-cadherin." (PMID 35455021, 2022). "Overexpression of TTYH1 is sufficient to promote the ability of cell migration and invasion in the TTYH1 non-expressed SaOS2 osteosarcoma cell." (PMID 35455021, 2022). "On the basis of these reports, it seems that unknown functioning of TTYH1 as a non-conducting protein might be important to understanding the roles of TTYH1 in the progression of osteosarcoma." (PMID 35455021, 2022).
epilepsy (2 papers, 2014 to 2021). A brain disorder characterized by episodes of abnormally increased neuronal discharge resulting in transient episodes of sensory or motor neurological dysfunction, or psychic dysfunction. "Seizures activate integrin signaling and induce a turnover in adhesive contacts, which hypothetically may be linked to increased Ttyh1 expression observed during epileptogenesis and epilepsy." (PMID 25316497, 2014).
status epilepticus (2 papers, 2014 to 2021). Status epilepticus is defined as a continuous seizure lasting more than 30 min, or two or more seizures without full recovery of consciousness between any of them. "We performed preliminary DAB immunostainings to detect Ttyh1 protein in slices from rats 24 h, 4 and 14 days after amygdala stimulation-induced status epilepticus and time-matched control animals." (PMID 25316497, 2014). "The results show the ubiquitous expression of Ttyh1 protein in astrocytes, oligodendrocytes and microglia in vitro and the increased expression of Ttyh1 in astrocytes in the hippocampus following status epilepticus." (PMID 25316497, 2014). "Moreover, using double immunofluorescence, we show Ttyh1 protein expression in activated astrocytes in the hippocampus following amygdala stimulation-induced status epilepticus." (PMID 25316497, 2014). "To test possibility that status epilepticus induces Ttyh1 expression also in oligodendrocytes or microglia, we performed double immunostainings using anti-Ttyh1 antibody and anti-Iba1 (microglia marker) or anti-Olig2 (oligodendrocyte marker) antibody (data not shown)." (PMID 25316497, 2014). "In addition, we analyzed the expression of Ttyh1 in glial cells in vitro and in vivo in the normal and injured brain following status epilepticus." (PMID 25316497, 2014).
Alzheimer disease (1 paper, 2021). A progressive, neurodegenerative disease characterized by loss of function and death of nerve cells in several areas of the brain leading to loss of cognitive function such as memory and language. "Microarrays also demonstrate brain location-dependent TTYH1 expression patterns in Alzheimer’s disease patients as the hippocampus and entorhinal cortex samples showed TTYH1 downregulation while superior frontal gyrus and middle temporal gyrus samples revealed TTYH1 (and TTYH2) upregulation." (PMID 34262434, 2021).
astrocytoma (1 paper, 2020). "Data point out that Ttyh1 is important for TM-dependent invasion and proliferation of astrocytoma cells, resulting in tumor progression in the brain." (PMID 32244839, 2020).
oligodendroglioma (1 paper, 2023). A well-differentiated (WHO grade II), diffusely infiltrating neuroglial tumor, typically located in the cerebral hemispheres. "This explanation accounts for the low expression levels of TTYH1 and GAP43 in oligodendrogliomas compared with those in astrocytomas." (PMID 37173982, 2023).
ovarian clear cell cancer (1 paper, 2021). An invasive malignant neoplasm that arises from the ovary and is characterized by a predominance of clear and hobnail malignant epithelial cells. "TTYH1 expression levels in human ES-2 ovarian clear cell carcinoma cell line were greatly higher in comparison with normal ovarian cells." (PMID 34729116, 2021). "TTYH1 was correlated to favorable prognosis with epithelial ovarian carcinoma, particularly in serous ovarian carcinoma, whereas the roles of TTYH1 in ovarian clear cell carcinoma or other kinds of OC remained unclear." (PMID 34729116, 2021).
Parkinson disease (1 paper, 2021). A progressive degenerative disorder of the central nervous system characterized by loss of dopamine producing neurons in the substantia nigra and the presence of Lewy bodies in the substantia nigra and locus coeruleus. "TTYH1, along with various other proteins associated with calcium homeostasis, were identified as having differential expression in Parkinson’s disease patients, suggesting a role of calcium homeostasis (and TTYH1’s association with it) in Parkinson’s disease pathogenesis." (PMID 34262434, 2021). "Additionally, mass-spectrometry demonstrated TTYH1 downregulation in the locus coeruleus of Parkinson’s disease patients when compared to controls." (PMID 34262434, 2021).